ADAM17 (ADAM metallopeptidase domain 17)
Diseases named in the same sentence as ADAM17 in open-access papers (continued):
Sharing a sentence is not in itself a finding about the gene and the disease.
ovarian carcinoma (continued). "HB-EGF, probably released via the actions of enzymes a disintegrin and metalloproteinase 17 (ADAM17) or cathepsin B, induces the transactivation of EGFR, which leads to increased proliferation of epithelial ovarian cancer cells." (PMID 35216283, 2022). "Ovarian cancer cell lines IGROV-1 and A2780, as well as primary patient-derived tumor cells obtained from tumor tissue and ascitic fluid, were cultured to analyze ADAM17 abundance in the culture supernatant." (PMID 34771725, 2021). "ADAM17 inhibitors (e.g., Aderbasib/INCB7839) have also already been under clinical investigation for various cancer types including lung and ovarian cancer with promising results." (PMID 33498866, 2021). "Furthermore, the application of ADAM17 as a clinical parameter for the detection of ovarian cancer must be qualified by the fact that other diseases, such as Alzheimer’s disease, rheumatoid arthritis, and ANCA-associated vasculitis, can also lead to elevated ADAM17 levels." (PMID 34771725, 2021). "In conclusion this report highlights the relevance of ADAM17 and AREG in ovarian cancer, and possibly opens up new directions to overcome platinum resistance in ovarian cancer treatment." (PMID 29662625, 2018). "In ovarian cancer, pharmacologic inhibition of ADAM proteins, or specific silencing of ADAM17/TACE, hampered shedding of CD166 expressed on the cell surface." (PMID 23940674, 2013). "The aim of this study is to investigate whether the ADAM17 substrates Nectin-4, Heparin-binding EGF-like growth factor (HB-EGF) and Amphiregulin (AREG) could function as potential tumor markers for ovarian cancer." (PMID 36497350, 2022). "Since higher ADAM17 concentrations have been detected in patients with EOC in the early stages, the combined use of CA125 and ADAM-17 could be used to detect ovarian carcinoma with better sensibility and specificity." (PMID 35216240, 2022). "In addition, a monoclonal antibody blocking ADAM17 activity inhibited shedding of the ADAM17 substrates TNF, TNFR1-alpha, TGF-alpha, AREG, HB-EGF and IL-6Ralpha and reduced tumor growth, in an ovarian cancer xenograft model." (PMID 36140519, 2022). "Our finding that ADAM17 is widely expressed in ovarian cancer cells is in line with previous studies, which report that positive IHC staining of ADAM17 is observed in the cytoplasm of tumor cells with no staining in normal ovarian epithelium." (PMID 36140519, 2022). "Therefore, in the present study, we evaluate the ADAM17 substrates Nectin-4, HB-EGF and AREG as a potential blood-based detection method for ovarian cancer." (PMID 36497350, 2022). "Many of the ADAM17 substrates, such as Nectin-4 and HB-EGF (heparin-binding epidermal growth factor-like factor) have already been investigated as potential tumor markers for ovarian cancer." (PMID 34771725, 2021). "To investigate whether chemotherapeutic treatment impacts ADAM17 activity, we determined the protein amounts of ADAM17 and its substrate AREG in ovarian cancer cell lines." (PMID 29662625, 2018). "In this study, we provide evidence that activity of ADAM17 and expression as well as shedding of the ADAM17 substrate AREG increase subsequently to chemotherapeutic treatment thus playing an important role in EGFR and ERK dependent chemo-sensitization of ovarian cancer cells." (PMID 29662625, 2018). "This combinatory effect of ADAM17 or ADAM10 inhibition and cisplatin treatment has not been shown before in ovarian cancer, to the best of our knowledge." (PMID 29662625, 2018).
colorectal cancer (34 papers, 2011 to 2025). A primary or metastatic malignant neoplasm that affects the colon or rectum. "Herein, we identified that colorectal cancer (CRC) cell-derived exosomal ADAM17 is strongly associated with metastasis in patients with CRC as well as with the metastatic ability of CRC cells." (PMID 34650435, 2021). "Especially, the expression of MCAM, NOX1, and ADAM17 was more prominent in the angiogenic, colorectal cancer-consensus molecular subtype 4 where high MCAM expression correlated with angiogenic and lymphangiogenic markers." (PMID 38137406, 2023). "Further along this line, exosomal ADAM17 was shown to promote the migration of colorectal cancer cells." (PMID 36293469, 2022). "ADAM17 can interact with cellular integrin α5β1 to promote the binding and uptake of exosomes derived from colorectal cancer." (PMID 36466812, 2022). "ADAM17 is also highly expressed in cervical cancer, liver cancer, colorectal cancer and bladder cancer." (PMID 36466812, 2022). "For example, miR-222 targets ADAM metallopeptidase domain 17 (ADAM17) to modulate multidrug resistance in colorectal carcinoma." (PMID 36428980, 2022). "To investigate if ADAM17 also plays a role in the interaction between colorectal cancer exosomes and PMCs, we obtained primary human PMCs from omentum samples of patients undergoing abdominal surgery." (PMID 34576100, 2021). "For example, endothelial cells release jagged 1, generated by proteolytic activity of ADAM metallopeptidase domain 17 (ADAM17) activating Notch in human colorectal cancer cells and thereby promoting a cancer stem cell phenotype and chemo-resistance." (PMID 34409045, 2021). "We report here that the interaction between integrin α5β1 on colorectal carcinoma cells and on PMCs and its ligand ADAM17 on exosomes mediates the binding and uptake of cancer-derived exosomes." (PMID 34576100, 2021). "Overexpression of ADAM17 promotes 5-fluorouracil resistance and metastasis in colorectal cancer cells via activation of the Notch signaling pathway, and induces metastasis in gastric cancer through activation of Notch and Wnt signaling pathways." (PMID 32986377, 2020). "ADAM17 was shown to negatively regulate c-MET signaling by increasing the levels of soluble MET in a KRAS mutant colorectal cancer model." (PMID 29230082, 2017). "For example, colorectal cancer-derived EVs (e.g., ADAM17 and miR-27b-3p) synergistically promote vascular leakage by interfering with the membrane localization of VE-cadherin and regulating the expression of tight junction proteins (ZO-1/occludin/Claudin5) via the KLF2/KLF4-VEGFR2 axis 92-94." (PMID 40521189, 2025). "Additionally, ADAM17 is highly expressed in drug-resistant colorectal cancer cells; however, miR-324-3p and miR-222 can suppress ADAM17 protein expression to restore drug sensitivity." (PMID 37175410, 2023). "In addition, in rectal cancer the SNP rs13403794 was detected, an SNP located upstream of ADAM17, which is a gene that is part of the signaling pathway involved in colorectal cancer progression and chemoresistance." (PMID 36077729, 2022). "Moreover, exosomal ADAM17 overexpression as well as RNA interference results highlighted its function as a tumor metastasis-promoting factor in colorectal cancer in vitro and in vivo." (PMID 34650435, 2021). "ADAM17 could regulate the chemical sensitivity of colorectal cancer stem cells by activating the Notch1 signaling pathway." (PMID 33535178, 2021). "Moreover, it was observed that CirExo-ADAM17 had a significant impact on the postoperative prognosis of patients with colorectal cancer." (PMID 34650435, 2021). "Furthermore, exosomal ADAM17 was shown to promote the migratory ability of colorectal cancer cells by cleaving the E-cadherin junction." (PMID 34650435, 2021). "Taken together, our current work suggests that exosomal ADAM17 is involved in pre-metastatic niche formation and may be utilized as a blood-based biomarker of colorectal cancer metastasis." (PMID 34650435, 2021).
colorectal cancer (continued). "Moreover, a recent study has shown that reducing ADAM17 levels has great pharmaceutical potential: reduced levels of ADAM17 in the Adam17ex/ex mouse limits colorectal cancer formation and any residual tumours are low-grade dysplasias." (PMID 29897336, 2018). "Here, although we observed a slight effect of Pacs2-deficiency in the context of intestinal inflammatory damage, loss of the ADAM17 fine-tuning function of PACS-2 was not sufficient to influence tumor formation driven by excessive Wnt signaling in the ApcMin model of colorectal cancer." (PMID 29312533, 2017). "We also investigated the potential clinical-pathological relevance of NOX1, ADAM17, and MCAM expression in colorectal cancer." (PMID 38137406, 2023). "Moreover, in accordance with our result, ADAM17 overexpression in exosomes increased the hepatic metastases rates of colorectal cancer cells in a murine model, whereas ADAM17 downregulation in exosomes eliminated the liver metastasis stimulation ability of exosomes on colorectal cancer cells." (PMID 36293469, 2022). "In colorectal cancer, the activation of epidermal growth factor receptors (EGF-R) included the processing of membrane-bound EGF-R which induced by ADAM17." (PMID 34182543, 2021). "The authors suggest that combination therapies of ADAM17 and c-MET inhibitors would be more clinically effective in KRAS mutant colorectal cancer." (PMID 29230082, 2017). "Moreover, ADAM17 has been described to be involved in EGF-R- mediated IL-6 synthesis and tumorigenesis in colorectal cancer." (PMID 34208863, 2021). "Moreover, the involvement of ADAM17 in colorectal cancer has been shown in a hypomorphic ADAM17 mouse model, which exhibits significantly reduced ADAM17 protein and no detectable ADAM17 cleaving activity." (PMID 31060243, 2019). "To test these hypotheses, we monitored NOX1, ADAM17, and mMCAM protein expression and performed co-immunoprecipitation (co-IP) experiments from whole lysates of human endothelial cells (HUVEC) and human colorectal cancer (CRC) cell lines (HCT-116, DLD1, and SW480)." (PMID 38137406, 2023). "Interestingly, ADAM17 protein levels were slightly, but non-significantly increased in exosomes isolated from peripheral blood of a small cohort of patients suffering from colorectal carcinoma (CRC)." (PMID 36078095, 2022). "In addition, expression levels of ADAM10, ADAM17, and ADAM19 were elevated in human colorectal carcinoma biopsy specimens compared to adjacent non-tumorous tissues." (PMID 33043016, 2020).
lung carcinoma (33 papers, 2006 to 2025). "ADAM17 is an emerging therapeutic target for lung cancer and its expression has been reported to be associated with SCZ." (PMID 38592583, 2024). "In a previous study, LTA was found to be related to SCZ in genetic polymorphism variant, and ADAM17 was identified as an emerging therapeutic target for lung cancer and its expression was revealed SCZ through the TNF pathway." (PMID 38592583, 2024). "ADAM17 is usually an oncogene and its upregulation is associated with the progression of lung cancer." (PMID 36466812, 2022). "Another large subset of variants was found in lung cancer (10.3%), in which ADAM17 has also been implicated." (PMID 33143292, 2020). "ADAM17 is overexpressed in many human cancers, including lung cancer, whereas genetic or pharmacological ablation of ADAM17 suppressed tumor proliferation and dissemination partly by promoting EGFR ligand release." (PMID 36720499, 2023). "Third, phosphorylation of iRhom2 is required for 14-3-3 binding in A549 cells, indicating that the phosphorylated iRhom2/14-3-3/ADAM17 activation pathway controls shedding of the ERBB ligands in these lung cancer cells." (PMID 35971826, 2022). "In this study, CD suppressed ADAM17 expression, especially in lung cancer, which supports the possibility of developing anti-SARS-CoV-2 drugs and suggests a role for CD in anti-SARS-CoV-2 therapy in cancer patients by inhibiting ADAM17 expression." (PMID 36558177, 2022). "We previously provided novel insights into IR-mediated activation of ADAM17 with subsequent substrate shedding in response to irradiation, and demonstrated that inhibition of ADAM17 sensitizes otherwise treatment-resistant lung carcinoma cells to IR." (PMID 36860547, 2021). "Once SDC1 is shed from the cell surface by ADAM17, the remaining transmembrane C-terminal fragment undergoes intramembrane proteolysis by γ-secretase and is degraded by the proteasome in A549 lung cancer cells." (PMID 34113616, 2021). "Here, we investigated the role of IR-induced ADAM17 matrix metalloproteinase activity for the intercellular communication between tumor cells and the tumor vasculature in non–small cell lung cancer (NSCLC) tumor models." (PMID 36860547, 2021). "Along with let-7, miR-145 and miR-222, which are directed against ADAM17, are also suppressed in lung cancer cells, possibly leading to higher expression rates of TMPRSS2 and ADAM17, which again would make the cells more susceptible to virus infection." (PMID 33271762, 2020). "In the context of lung cancer, it will be of interest to assess the driver role of ADAM17 in other lung cancer subtypes (e.g., KRAS wild-type LAC, EGFR mutant LAC, squamous cell carcinoma)." (PMID 31438559, 2019). "Finally, miR-152 and miR-326 have been reported to inhibit cell proliferation, colony formation, migration, and invasion by silencing ADAM17 expression in lung cancer." (PMID 37175410, 2023). "Moreover, in a nicotine-derived nitrosamine ketone model of tobacco-related lung cancer, genetic or pharmacologic blockade of ADAM17 led to a significant reduction of lung lesions and concomitant reduced sIL-6R levels." (PMID 31694340, 2019). "ADAM-17 has thus been presented as a potent target in breast and lung cancers." (PMID 23028451, 2012). "Moreover, ADAM17 inhibition may serve as a new indirect avenue to target the oncogenic activities of mutant KRAS in cancers including lung cancer (i.e., LAC), CRC and pancreatic cancer." (PMID 31438559, 2019). "ADAM17 can shed amphiregulin, transforming growth factor α and other EGFR ligands, it can also activate the EGFR to thereby improve the lung cancer cell proliferation and cell motility capacity." (PMID 25351873, 2015). "An active ADAM17 regulates EGF receptor expression through activating NOTCH1 that was demonstrated to affect proliferation and survival of lung cancer cells, and tumorigenicity of non-small cell lung cancer." (PMID 22239941, 2012).
lung carcinoma (continued). "Also, regarding the importance of SLC3A2-NRG1 fusion in lung cancer, in another study, it was shown that KRAS enhances tumor growth in SLC3A2-NRG1–positive lung cancer cells through ADAM17-mediated NRG1 cleavage." (PMID 38705513, 2024). "However, the protease TACE, a member of ADAM family (ADAM 17), was activated by the serine protease activity of A. fumigatus in lung carcinoma cells, which in turn cleaved TGF‐α from the cellular membrane." (PMID 37357550, 2023). "ADAM17 expressions in lung cancer were increased, but not significantly compared to normal tissues in the TCGA dataset (Data not shown)." (PMID 35720350, 2022). "In this regard, ADAM17 is overactivated via p38 MAPK-mediated threonine phosphorylation, following which, activated ADAM17 drives the preferential processing of the sIL-6R, which induces lung cancer cell proliferation through ERK1/2 MAPK activation." (PMID 31438559, 2019). "ADAM17 has been shown to shed ligands of EGFR, such as amphiregulin and TNFα, and subsequently activate EGFR, thereby improving the proliferation and migration of lung cancer cells." (PMID 25364437, 2014). "However, on the other hand, inactivating NOTCH1 or ADAM17 resulted in substantial cell death, while EGFR inhibition predominantly induced cell arrest in lung cancer." (PMID 22239941, 2012). "Monocytes from lung cancer patients produce elevated levels of mature TNF-α which could result from the shedding of pro-TNF-α by ADAM-17 (TACE)." (PMID 16495931, 2006). "Similarly, in lung cancer, the circRNAs, namely, hsa_circ_0051620| SLC1A5 and hsa_circ_0066954| POLQ, are upregulated and are shown to interact with and regulate driver genes, namely, ADAM17, CDH2, RUNX2, and ZBTB18, through miR-338-3p." (PMID 34055888, 2021). "Notably, the predominant role of ADAM17 in mediating the pathological consequences of deregulated sIL-6R-driven IL-6 trans-signaling has recently been reported in Kras mutant LAC and cigarette smoke carcinogen (NNK)-induced lung cancer." (PMID 31438559, 2019). "However, in contrast to our current study, the clinical utility of ADAM17 specifically in mutant KRAS LAC (which accounts for ~15% of all lung cancers) was not investigated." (PMID 30833304, 2019).